ZNF292 (zinc finger protein 292)
Description:
May be involved in transcriptional regulation.
Synonyms: KIAA0530; ZFP292; bA393I2.3; Zn-15; Zn-16; MRD63; MRD64; Nbla00365
Tractability: PROTAC: ubiquitination databases record sites on it; its protein half-life has been measured.
Gene: Protein-coding gene on chromosome 6 (87,151,803 to 87,265,943, forward strand). Ensembl gene ENSG00000188994.
Subcellular location: Nucleus
Subcellular location (Human Protein Atlas): Nuclear membrane; Nucleoplasm
Gene Ontology:
Molecular function: DNA binding; DNA-binding transcription factor activity, RNA polymerase II-specific; DNA-binding transcription activator activity, RNA polymerase II-specific
Biological process: regulation of transcription by RNA polymerase II; positive regulation of transcription by RNA polymerase II
Cellular component: nucleus
Genetic constraint (gnomAD): Loss-of-function variants: 22 observed, 195.32 expected, observed/expected ratio (o/e) 0.11, 90% interval 0.079 to 0.16. The upper end of that interval is the gene's LOEUF score, 0.16, which puts it in group 1 of 6, group 1 being the genes least tolerant of losing a copy. Missense variants: 2,867 observed, 3,180 expected, observed/expected ratio (o/e) 0.9, 90% interval 0.87 to 0.93. Synonymous variants: 1,237 observed, 1,131.7 expected, observed/expected ratio (o/e) 1.09, 90% interval 1.04 to 1.15.
Gene-disease validity (ClinGen):
ClinGen rates the evidence that ZNF292 causes each of these diseases.
complex neurodevelopmental disorder (autosomal dominant): Definitive. A disorder that involves more than one phenotype associated with the central nervous system, including but not limited to intellectual disability, autism, and seizures (epilepsy).
Homologues: Orthologues: chimpanzee ZNF292 (99% identical), macaque ZNF292 (98% identical), dog ZNF292 (93% identical), pig ZNF292 (93% identical), rabbit ZNF292 (92% identical), guinea pig ZNF292 (83% identical), rat Zfp292 (82% identical), mouse Zfp292 (81% identical), tropical clawed frog ZNF292 (45% identical), zebrafish znf292b (32% identical), zebrafish znf292a (26% identical). Paralogues in human: RLF (22% identical), ZNF654 (11% identical).
Diseases named in the same sentence as ZNF292 in open-access papers:
ZNF292 is named in the same sentence as 35 diseases in open-access papers, as found by Europe PMC text mining. Sharing a sentence is not in itself a finding about the gene and the disease. The quoted sentences say what the papers report.
autism (4 papers, 2018 to 2024). Persistent deficits in social interaction and communication and interaction as well as a markedly restricted repertoire of activity and interest as well as repetitive patterns of behavior. "There is one report of likely disruptive variants in ZNF292 being associated with autism and we observed autism in 4/10 individuals with a ZNF292 deletion." (PMID 29904178, 2018). "Genes located in proximal 6q that have been linked to autism are RIMS1 (regulating synaptic membrane exocytosis 1, MIM*606629), PHIP, SYNCRIP and ZNF292 (zinc finger protein 292, MIM*616213)." (PMID 29904178, 2018). "Only TNRC6B, NCKAP1, and one of the two ZNF292 LGD DNMs occur in autism patients with an IQ in the normal range." (PMID 30564305, 2018). "ZNF292, encoding a zinc finger protein, is listed as a SFARI autism gene designated 1S (syndromic)." (PMID 38649688, 2024). "One study employing a large cohort of the ASD probands obtained from the Autism Clinical and Genetic Resourced in China (ACGC) indicated ZNF292 as a novel autism risk gene, as the patients harboring various mutations in this gene demonstrated ID and severe language impairment." (PMID 32117005, 2020). "ZNF292, which has not been reported as significant in previous studies, was implicated as a novel autism risk gene in the ACGC cohort by both models (q = 0.014, CH model; q = 0.016, denovolyzeR model)." (PMID 30564305, 2018).
colorectal cancer (4 papers, 2018 to 2025). A primary or metastatic malignant neoplasm that affects the colon or rectum. "The ZNF292 gene is a tumor suppressor gene, and mutations in this gene have been reported to be associated with the development of gastric cancer, colorectal cancer, and leukemia." (PMID 41294667, 2025). "ZNF292 is a transcription factor-encoding gene and is considered as a candidate tumor suppressor in gastric and colorectal cancer." (PMID 33201835, 2020). "The Zinc finger transcription factor, ZNF292 was shown to function as a tumor suppressor in gastric cancer, colorectal cancer, and chronic lymphocytic leukemia." (PMID 30150711, 2018). "ZNF292 is considered to be a potential suppressor gene (TSG) of gastrointestinal cancer (gastric cancer, liver cancer and colorectal cancer)." (PMID 36387908, 2022).
prostate carcinoma (4 papers, 2017 to 2024). A carcinoma that arises from epithelial cells of the prostate gland. "ZNF292 was mutated on the remaining allele in one patient and has been found to be rearranged in prostate cancer." (PMID 28945760, 2017). "For example, loss of CHD1 and ZNF292 occurs at a later stage in ERG-positive tumors than in ERG fusion–negative tumors, but as these lesions are common to both progression pathways, these genes seem to be key drivers of prostate cancer progression." (PMID 39347576, 2024). "Deletion of ZNF292 in prostate cancer results in decreased expression, which may promote tumor development." (PMID 30150711, 2018). "In addition to confirm several previous studies, we found novel recurrent SCNA for ERG-negative prostate cancers, such as ZNF292 deletion." (PMID 30150711, 2018).
developmental delay (3 papers, 2018 to 2025). "The association between ZNF292 mutations and short stature with developmental delay adds a new layer to the heterogeneous etiology of growth disorders." (PMID 40777882, 2025). "ZNF292‐related disorders included developmental delays and ID." (PMID 40777882, 2025). "Notably, the co‐occurrence of developmental delay and absence of syndromic features should prompt ZNF292 screening, particularly in exome‐negative idiopathic cases." (PMID 40777882, 2025).
glioma (3 papers, 2016 to 2022). A benign or malignant brain and spinal cord tumor that arises from glial cells (astrocytes, oligodendrocytes, ependymal cells). "This is the case of GATA3 in breast tumors, ZNF292 in low grade gliomas, ARID5B in uterine carcinomas, and MYC in diffuse B-cell lymphomas." (PMID 26792175, 2016). "In human glioma cell lines, circ-ZNF292 silencing decreased tube development." (PMID 35883576, 2022). "The circ-ZNF292 is involved in the development of human glioma tubes." (PMID 35883576, 2022). "Circ-ZNF292 is required for the proliferation and tube development of gliomas." (PMID 35883576, 2022).
hepatoma (3 papers, 2021 to 2025). "Highly expressed circRNA ZNF292 represented radioresistance in hepatoma cell." (PMID 35372031, 2022). "CircRNA ZNF292 can be induced in hypoxia-responsive human hepatoma cell." (PMID 35372031, 2022). "Knockdown of circRNA ZNF292 (cZNF292) increased SOX9 nuclear translocation, subsequently reduced Wnt/β‐catenin pathway activity, leading to suppression of VM in hypoxic hepatoma cell." (PMID 39964093, 2025).
leukemia (3 papers, 2025). A malignant (clonal) hematologic disorder, involving hematopoietic stem cells and characterized by the presence of primitive or atypical myeloid or lymphoid cells in the bone marrow and the blood. "Analogous to BRCA1, loss of ZNF292 function might impair DNA damage repair, theoretically increasing susceptibility to solid tumors or leukemias." (PMID 40777882, 2025). "Other genes like ZNF292, PRDM1, and CDH11 demonstrated promoter active demethylation and were previously linked to different leukemia types, where PRDM1 and CDH11 were reported to be frequently epigenetically silenced in these tumors." (PMID 41516186, 2025).
bladder cancer (2 papers, 2020 to 2022). "A ZNF292-spliced circRNA, has-circRNA-403658, is upregulated in hypoxia-induced bladder cancer cells." (PMID 32513983, 2020).
breast carcinoma (2 papers, 2020 to 2022). "In the present study, ZNF292 expression is associated with decreased RFS of breast cancer patients." (PMID 33201835, 2020). "Oncogenic genes like FAM83D, CTDSP1, and SAPCD2 were downregulated in all three cells, and tumor suppressor genes (TSGs) like ZNF292, ANKRD12, NKAPL, and CCL21 were upregulated in all three breast cancer cells upon curcumin treatment." (PMID 34981672, 2022).
liver cancer (2 papers, 2022 to 2025). An epithelial or non-epithelial malignant neoplasm that arises from the liver. "Meanwhile, ZNF292 is also a tumor suppressor gene (TSG), which may play an important role in colorectal and liver cancers." (PMID 40777882, 2025).
melanoma (2 papers, 2020 to 2024). A malignant, usually aggressive tumor composed of atypical, neoplastic melanocytes. "The zinc finger protein 292 (ZNF292) gene was reported to be a target gene regulated by HIF1α in melanocytes whose gene expression change under hypoxia and was associated with primary human melanoma tumours." (PMID 39199954, 2024). "However, high expression of ZNF292 is significantly correlated with reduced time of disease-free status in melanoma." (PMID 33201835, 2020).
attention deficit-hyperactivity disorder (1 paper, 2025). A disorder characterized by a marked pattern of inattention and/or hyperactivity-impulsivity that is inconsistent with developmental level and clearly interferes with functioning in at least two settings (e.g. at home and at school). "Although IDs and attention deficit hyperactivity disorder were reported in ZNF292 as mostly clinical phenotypes, the patient in our case has not exhibited clinical manifestations with neurological symptoms yet." (PMID 40777882, 2025).
autism spectrum disorder (1 paper, 2025). A spectrum of developmental disorders that includes autism, and Asperger syndrome. "Pathogenic mutations in the ZNF292 gene are a significant genetic cause of Intellectual Developmental Disorder (IDD) in individuals, manifesting with a spectrum of clinical features including mild to severe intellectual impairment, speech delay, and co‐occurring autism spectrum disorder (ASD)." (PMID 40777882, 2025).
bone marrow cancer (1 paper, 2025). "Furthermore, mutations in the ZNF292 gene have been found in liver, colon, gastric, and bone marrow cancers." (PMID 40777882, 2025).
congenital heart disease (1 paper, 2025). A heart disease that is present at birth. "Unlike Noonan syndrome (PTPN11 mutations), ZNF292 cases rarely exhibit facial dysmorphism or congenital heart disease, while their normal IGF‐1 levels distinguish them from GH deficiency." (PMID 40777882, 2025).
intellectual disabilities (1 paper, 2022). "The ZNF292 variant was first reported in 28 families with intellectual disabilities in March 2020." (PMID 35346031, 2022).
Macrocephaly (1 paper, 2018). Occipitofrontal (head) circumference greater than 97th centile compared to appropriate, age matched, sex-matched normal standards. "We identified a potential novel risk gene (ZNF292), one novel gene with recurrent LGD DNMs (RALGAPB), as well as genes associated with macrocephaly (GIGYF2 and WDFY3)." (PMID 30564305, 2018).
Turner syndrome (1 paper, 2025). Turner syndrome is a chromosomal disorder associated with the complete or partial absence of an X chromosome. "While traditional diagnostic algorithms prioritize endocrine testing (e.g., GH‐IGF1 axis, thyroid function) and chromosomal analysis (e.g., Turner syndrome), our data suggest that ZNF292 defects represent a non‐syndromic genetic form with unique molecular signatures." (PMID 40777882, 2025).
tumor (14 papers, 2015 to 2025). "Integrating ZNF292 into diagnostic workflows refines the classification of syndromic short stature, while its putative tumor‐suppressor function calls for long‐term oncologic vigilance." (PMID 40777882, 2025). "Research has shown a strong correlation between the silencing of ZNF292 and the presence of gain‐of‐function mutations in ZNF292 with tumorigenesis and tumor metastasis in humans." (PMID 40777882, 2025). "The ZNF292 gene has been identified as a tumor suppressor that plays a crucial role in the development and advancement of tumors." (PMID 40777882, 2025). "The deletion of the tumor suppressor ZNF292 on 6q14.3 also seems to be an early driving event in ERG fusion–negative tumors." (PMID 39347576, 2024). "PKP2, TXN, and ZNF292 are also abnormally expressed in tumors and induce radioresistance of tumor cells." (PMID 37101691, 2023). "Our qRT-PCR analysis demonstrated that STMN1 and ZNF292 were overexpressed in tumor samples, while PRKACB expression was higher in paracancerous samples." (PMID 33201835, 2020). "Several of the remaining 21 genes not in the GS, such as MYH14, MED23, and ZFP36L1 in BRCA, and ZNF292, FUBP1, and DTX1 in CLL, had also been implicated in tumor development." (PMID 29030609, 2017). "Numerous research studies have identified ZNF292 as a gene involved in suppressing tumors, characterized by its significantly higher expression in normal tissues adjacent to tumors compared to its lower expression levels within the tumor tissues." (PMID 40777882, 2025). "Other 6q15 genes with potential tumor suppressive functions for example include EEF1A1, ZNF292, SNORD50A, PRDM1, CCNC, FOXO3, WISP3, and FRK." (PMID 34625909, 2022). "Consistent with our qRT-PCR results, ZNF292 and STMN1 staining were higher in tumor samples, while staining of PRKACB was lower in tumor." (PMID 33201835, 2020). "We found that down regulation of each of 4 genes, i.e., SMAP1 (6q13), ZNF292 (6q14), HMGN3 (6q14), and UBE2J1 (6q15) significantly increased cell growth over background in colony formation assays performed in duplicate (P ≤ 0.0139), thus supporting a tumor suppressive role for these four genes." (PMID 29312579, 2017).
ZNF292 also shares sentences with these, for which no sentence is quoted: cancer (3 papers); gastric cancer (3); and speech delays (1); breast tumors (1); chronic lymphocytic leukemia (1); epilepsy (1); genetic disease (1); growth disorders (1); intellectual impairment (1); invasive breast carcinoma (1); Noonan syndrome (1); parkinsonian disorder (1); prostate adenocarcinoma (1); sarcoma (1); unipolar depression (1); uterine carcinoma (1).